INS (insulin)
Diseases named in the same sentence as INS in open-access papers (continued):
Sharing a sentence is not in itself a finding about the gene and the disease.
Hyperinsulinemia (continued). "IR is due to the decreased efficiency of insulin in promoting glucose uptake and utilization, and the body's compensatory production of excessive insulin produces hyperinsulinemia to maintain blood glucose stability." (PMID 34272768, 2021). "Liver-specific knockout of IR in mice and mice deleted of CEACAM1 develop hyperinsulinemia, implying that insulin action and production are essential endosomal responses that limit anabolic processes to nutrient oversupply." (PMID 33494161, 2021). "Some consequences of IR, including acanthosis nigricans and ovarian enlargement, require hyperinsulinemia, and presumably reflect increased insulin action." (PMID 33901270, 2021). "Insulin-sensitizers, mainly metformin, are proposed in subjects with hyperinsulinemia to ameliorate the metabolic profile." (PMID 33917519, 2021). "Increased insulin levels contribute to hepatic insulin receptors' downregulation, triggering, and sustaining hyperinsulinemia." (PMID 34099024, 2021). "Several physiological conditions are able to impair the insulin action like hypercaloric diet, weight gain, inflammatory states, sympathetic stimulation, and hyperinsulinemia." (PMID 32737757, 2021). "Skeletal muscle is the primary tissue responsible for post prandial glucose disposal, suggesting that skeletal muscle insulin sensitivity is maintained in DKI mice despite hyperinsulinemia and whole-body glucose intolerance." (PMID 34502525, 2021). "For instance, it has been reported that hyperinsulinemia and IR are involved with hyperandrogenism, since insulin stimulates the production of ovarian androgens in synergy with luteinizing hormone." (PMID 33953699, 2021). "The aim of this study was to assess serum SFRP5 concentration in a young healthy population in relation to insulin sensitivity and its regulation by hyperinsulinemia and/or serum free fatty acids (FFA) elevation." (PMID 34184187, 2021). "Most interestingly, basal Fetuin-B level were related to short- and long-term improvement of adipose insulin sensitivity inhibiting lipid breakdown during hyperinsulinemia." (PMID 34611132, 2021). "Insulin remains present in higher concentrations, and in order to counteract cell resistance, the organism produces even more significant amounts of insulin, its level in the blood increases, and hyperinsulinemia occurs." (PMID 35056318, 2021). "Exposure to the higher BPA dose resulted in hyperinsulinemia, with plasma insulin levels comparable to those in late pregnancy." (PMID 33467592, 2021). "Excess FFA are in part due to increased caloric intake and obesity as well as adipocyte resistance to insulin leading to lypolysis and hyperinsulinemia." (PMID 33681089, 2021). "These clinical conditions share a state of resistance to insulin-mediated glucose disposal that, together with compensatory hyperinsulinemia, have been shown to be independent predictors for all of them." (PMID 34362033, 2021). "Most cross-sectional studies have shown a positive association between serum 25(OH)D levels and measures of insulin sensitivity derived from a hyperinsulinemia euglycemic clamp test or indirect markers such as the quantitative insulin sensitivity index." (PMID 34684492, 2021). "This is noteworthy given that numerous studies have found that insulin clearance is decreased in individuals of African descent, compared to other racial groups, and is a driver of hyperinsulinemia." (PMID 34206745, 2021). "More specifically, it is believed to be a result of altered liver function, impaired insulin clearance, and pancreatic β-cell dysfunction, leading to hyperinsulinemia and defective use of blood glucose." (PMID 33445629, 2021). "On the other hand, combinations of IR and compensatory hyperinsulinemia (in T2D) or with hyperinsulinemia induced by insulin therapy (in T1D) have also been reported as capable of causing damage to various organ systems." (PMID 35011666, 2021).
Hyperinsulinemia (continued). "It is well established that at 10 days of age, db/db mice start to display hyperinsulinemia and between 8 and 12 weeks of age the concentration of insulin reaches a maximum of approximately 6–10 times the normal levels (0.8–1.2 ng/mL)." (PMID 34113829, 2021). "It was chosen over insulin to estimate neonatal hyperinsulinemia, as C-peptide has a long half-life and is unaffected by several blood processing conditions such as hemolysis." (PMID 33596873, 2021). "Mice that have the inflammatory pathway of NF-ĸB disabled (IKKβ knockout) are more insulin sensitive and are partially protected from high fat diet induced glucose intolerance and hyperinsulinemia." (PMID 33505701, 2021). "When IDE is occupied degrading excess insulin in conditions of hyperinsulinemia, Aβ is left to steadily accumulate in both peripheral circulation and centrally, intensifying the conditions of AD induced by Aβ accumulation." (PMID 34497507, 2021). "In insulin-resistant conditions, the β-cells of the pancreas compensate by escalating insulin secretion to produce hyperinsulinemia." (PMID 33801684, 2021). "Measurement of serum insulin levels indicated basal hyperinsulinemia in one of the six horses (Horse 2), interpreted as ID." (PMID 33915682, 2021). "In a healthy individual, a maximum one-fifth overturn of hyperinsulinemia has been reported to occur through insulin-driven gluconeogenesis in the liver, which also suppresses glycogenolysis almost completely." (PMID 34203830, 2021). "Nevertheless, even if the relevance of insulin in tumor initiation is still a controversial issue, many in vivo and in vitro observations actually link hyperinsulinemia to cancer promotion and progression." (PMID 34681797, 2021). "C-peptide is produced in equal amounts to insulin and can be used to assess endogenous insulin secretion; thus it is considered as a valid marker of hyperinsulinemia in the long-term period." (PMID 33892738, 2021). "As insulin has strong antilipolytic effects, hyperinsulinemia will initially result in excess fat accumulation." (PMID 34360563, 2021). "In addition, acute euglycemic hyperinsulinemia decreased fractional UA excretion by 26 % (from 6.1 ± 0.8 % to 4.5 ± 0.6 %) in healthy subjects, indicating that insulin inhibits renal UA excretion and that high UA levels causes insulin resistance by affecting the insulin signaling pathways." (PMID 33593356, 2021). "Hyperinsulinemia was defined as a fasting insulin ≥15 mU/L, and/or insulin levels at 2 h ≥80 mU/L during OGTT." (PMID 33935964, 2021). "The reduced hyperinsulinemia observed in PBA-treated mice is in line with the reported insulin-sensitizing effects of chemical chaperones, including PBA, on peripheral tissues." (PMID 34088954, 2021). "Actually, AD has been also defined as brain-specific or type 3 diabetes, since one of the hallmarks of AD is also a reduction of the level of the cerebral insulin signaling, which is possibly related to hyperinsulinemia." (PMID 33946461, 2021). "When cut-offs are available for hyperinsulinemia, these are in most cases based on fasting insulin levels." (PMID 34360563, 2021). "The data presented in this review indicate that insulin resistance, change of Akt/FoxOs axis in metabolic organs such as the liver and muscles during aging leads to aging metabolism such as hyperinsulinemia, hyperlipidemia, and age-related metabolic changes." (PMID 34631216, 2021). "Despite signs of hyperinsulinemia, normal insulin sensitivity and improved glucose tolerance were observed in the young and aged CD-fed ASKO mice." (PMID 32797353, 2021). "The accumulation of excessive insulin in the blood, described as hyperinsulinemia, with normal blood glucose levels indicates the presence of IR." (PMID 33935964, 2021).
Hyperinsulinemia (continued). "Male C57BL/6 J mice fed a high-fat/high-sucrose (HFHS) diet and treated with lingonberry extract for 8 weeks had lower fasting and postprandial hyperinsulinemia, improved insulin sensitivity, and enhanced hepatic insulin clearance." (PMID 34066191, 2021). "On the other hand, in T2DM, insulin concentration, which plays a role as a competitive substrate for the insulin-degrading enzyme, is increased via peripheral hyperinsulinemia." (PMID 33747345, 2021). "Since no group differences were found for amino acids when disregarding the insulin concentration, it is possible that this supposed insulin resistance was offset by hyperinsulinemia." (PMID 33509165, 2021). "The observed hyperinsulinemia is largely a consequence of Akt2 inhibition, which is the major Akt isoform expressed in insulin-responsive tissues and particularly in the liver." (PMID 35578699, 2021). "Fetal hyperinsulinemia has been documented in diabetic pregnancies by analysis of total insulin, C-peptide, and free insulin in umbilical vein plasma." (PMID 33803995, 2021). "Our study demonstrated hyperinsulinemia and reduced insulin sensitivity (ISOGTT) of acromegalic patients with NGT compared with healthy subjects." (PMID 34917145, 2021). "Hyperinsulinemia has been linked to both CMD dysfunction and AD pathology, and it highlights the close relationship between Aβ and insulin via insulin degrading enzyme (IDE)." (PMID 34497507, 2021). "Hyperinsulinemia, which can contribute to common defects in insulin/IGF-1 pathways on the pancreatic periphery and in the pancreatic islet β-cell, is considered a key causative factor for the development of DM II." (PMID 34208601, 2021). "Lean normoglycemic ZDF with mild hyperinsulinemia and lean normoglycemic ZF rats with normal fasting plasma insulin (normoinsulinemia) displayed intermediary GPI-AP transfer, which was slightly above that of lean normoglycemic normoinsulinemic Wistar rats." (PMID 34680568, 2021). "It is generally accepted that the stimulating effect of hyperinsulinemia on the production of androgens by ovarian cells is based on low affinity binding of insulin with IGF-1 receptors." (PMID 33429918, 2021). "As a result, the pancreatic islet cells of the fetus are stimulated to secrete insulin, leading to fetal hyperinsulinemia." (PMID 34556066, 2021). "Our molecular data showed that diet-induced prediabetic hyperinsulinemia resulted in impaired insulin signaling and multiple postreceptor intracellulardefects including impaired glucose transport and metabolism." (PMID 33708999, 2021). "Several symptoms of PCOS are boosted by hyperinsulinemia; a rise in insulin levels appears to promote androgen ovarian secretion, action, and an increase in weight." (PMID 34357331, 2021). "Infertile women with PCOS had higher levels of fasting insulin, and the resultant hyperinsulinemia plays a role in the pathogenesis of reproductive disorders." (PMID 34552564, 2021). "HFD obese prediabetic mice robustly and consistently develop elevated fasting blood glucose (FBG), impaired insulin sensitivity, hyperinsulinemia, dyslipidemia, and both small- and large-fiber PN." (PMID 33692086, 2021). "The second pathway is related to a reduced insulin sensitivity resulting in compensatory hyperinsulinemia." (PMID 34140596, 2021). "On the other hand, female rats exposed to DHT show hyperinsulinemia due to increased insulin gene transcription in pancreatic beta cells." (PMID 34220716, 2021). "Many studies define hyperinsulinemia based on arbitrarily chosen cut-off fasting insulin concentrations or 2 h insulin concentrations after an oral glucose load (for example, >67th percentile, >75th percentile or >90th percentile for non-diabetic subjects)." (PMID 34360563, 2021).
Hyperinsulinemia (continued). "In this study, we demonstrated that, in lean mice, 6 weeks exposure to IH is responsible for hyperinsulinemia, systemic insulin resistance, cardiac insulin signaling modifications, cardiac interstitial fibrosis, and increased cardiac contractility." (PMID 33682327, 2021). "Among these factors are the severity of hyperinsulinemia and HA, the blood levels of the binding proteins for insulin, IGF-1 (IGFBP-1) and androgens (SHBG), and the blood levels of AMH and HDL-C." (PMID 33429918, 2021). "Diets with high dietary fiber intake show a low glycemic index, wherein even the same amount of calories can reduce postprandial hyperinsulinemia, easily reduce body fat, and improve insulin sensitivity." (PMID 33829033, 2021). "Insulin is a major regulator of protein metabolism, with hyperinsulinemia having been shown to decrease plasma amino acid concentration by altering amino acid utilization and protein turnover in several mammalian tissues including skeletal muscle and skin." (PMID 33704816, 2021). "Mice genetically ablated for α-syn became glucose intolerant and insulin resistant with hyperinsulinemia and reduced glucose-stimulated insulin secretion (GSIS)." (PMID 34393754, 2021). "Historically, elevated SUA levels in MS has been attributed to hyperinsulinemia, since insulin reduces renal excretion of uric acid." (PMID 33604722, 2021). "Since insulin secretion and clearance decline with age, hyperinsulinemia seems to be maintained, primarily, due to a decrease in the insulin clearance." (PMID 34054736, 2021). "Hyperinsulinemia is a well-known driver of tumor growth and progression, and thus future investigations to measure circulating insulin as well as tissue-specific changes in insulin sensitivity in response to moringa are warranted." (PMID 34578801, 2021). "Decreased levels of insulin and IR are found in the cerebrospinal fluid (CSF) of AD patients due to long-term peripheral hyperinsulinemia and decreased insulin transport across the blood-brain barrier (BBB)." (PMID 34349617, 2021). "Accruing evidence shows that insulin facilitates memory and cognition under normal conditions whereas chronic hyperinsulinemia impairs them." (PMID 34349617, 2021). "In humans, there are at present three main strategies to prevent and manage hyperinsulinemia: reducing calorie intake, increasing hepatic insulin clearance and maximizing insulin sensitivity." (PMID 34360563, 2021). "This will make pancreatic β-cells produce extra insulin in an attempt to normalize glucose levels, thus resulting in hyperinsulinemia." (PMID 33806509, 2021). "Until beta cell failure occurs, this is compensated for by hyperinsulinemia, with plasma insulin concentration raised by 1 or 2 orders of magnitude in severe cases." (PMID 33901270, 2021). "On the other hand, L-IDE-KO mice fed a HFD also show a ~30% reduction in IR levels, but also exhibit hyperinsulinemia, which would theoretically permit maximal insulin action." (PMID 33477364, 2021). "Plasma insulin levels were unaltered after glucose administration, excluding a compensatory hyperinsulinemia to maintain blood glucose levels." (PMID 34211098, 2021). "During the HEC, the blood glucose was clamped at the basal level (~ 5mmol), and insulin levels were significantly elevated from 48.3 ± 13.2 to 348.3 ± 52.4 pmol/L, indicating hyperinsulinemia in vivo." (PMID 34867822, 2021). "Insulin seems to play a significant role in the development of plaques, and hyperinsulinemia observed in IR leads to their formation." (PMID 34208833, 2021). "Following the injection of recombinant BMPER into HFD-fed mice, we detected significant normalization of hyperinsulinemia and improved glucose and insulin tolerance responses." (PMID 33772019, 2021). "Lorcaserin can restrain patients’ appetite and improve insulin sensitivity and hyperinsulinemia mainly through activating 5-HT2CR in the hypothalamus." (PMID 34803706, 2021).
Hyperinsulinemia (continued). "Together, these data suggest that both insulin biosynthesis and insulin vesicle release are augmented in Csn2WT/K70E mice, resulting in hyperinsulinemia." (PMID 33911083, 2021). "Due to the abundant expression of Irs1 in the PV zone, insulin signaling is considered to be rather enhanced in the presence of hyperinsulinemia despite the downregulation of Irs2, resulting in increased lipogenesis and development of steatosis." (PMID 33923817, 2021). "In the presented study we have investigated the effects of calystegines from Hyoscyamus albus on HepG2 cells in which hyperinsulinemia and glucotoxicity was induced by the treatment with insulin and glucose." (PMID 34034759, 2021). "Glucose tolerance tests performed in the parents revealed normal glucose tolerance but mild hyperinsulinemia (insulin at 0 and 120 minutes: 14.25 and 148.3 mU/L, 15.6 and 109.3 mU/L in the mother and father, respectively)." (PMID 33995269, 2021). "In this regard, plasma insulin is usually elevated (due to compensatory hyperinsulinemia) under low-grade chronic inflammation conditions." (PMID 33924538, 2021). "Our data suggests that aging and unsustainable life is associated with development of disproportionality between bone and the growing body size, partly due to insulin reversal from hyperinsulinemia during late life." (PMID 33744845, 2021). "IR impairs glucose metabolism and results in a compensatory increase in beta-cell insulin production and hyperinsulinemia." (PMID 35360506, 2021). "Decreased insulin sensitivity leads to hyperinsulinemia possibly leading to insulin-induced competitive inhibition of IDE activity." (PMID 33925119, 2021). "We reported a significant decline in skeletal muscle insulin clearance during physiologic hyperinsulinemia, indicative of a saturable transport process." (PMID 33466380, 2021). "Women with PCOS experienced a reduction in body weight, blood glucose and insulin levels after 12 weeks on such a diet, correcting hyperinsulinemia and HOMA-IR and, consequently, improving body composition." (PMID 34071499, 2021). "Given that AD patients tend to present hyperinsulinemia and decreased insulin sensitivity, we believe that the beneficial effects of APN in both the OB and the HIPP are mediated by the sensitization of InsR." (PMID 33653273, 2021). "During hyperinsulinemia, Aβ and insulin both compete for IDE action, resulting in Aβ accumulation and plaque formation." (PMID 34497507, 2021). "Recent data indicated that hyperinsulinemia promotes PanIN formation in KrasG12D mice, an effect relying on the mitogenic activity of insulin." (PMID 34202040, 2021). "Previous studies have shown that hyperinsulinemia can increase insulin secretion by increasing intracellular signaling and sensitivity of beta cells in response to insulinotropic agents and beta-cell hypertrophy." (PMID 33985566, 2021). "The compensatory hyperinsulinemia arising due to insulin resistance leads to a higher production of hIAPP and increases endoplasmic reticulum stress, which exacerbates β-cell demise, in turn leading to greater insulin/IAPP production in the surviving β-cells." (PMID 33467592, 2021). "Hyperinsulinemia is also induced by impaired hepatic insulin clearance in diseases such as fatty liver, which is known to be associated with arteriosclerosis." (PMID 34518649, 2021). "The increased IR and compensatory high insulin concentrations (hyperinsulinemia) play important roles in the progression of PCOS." (PMID 34484117, 2021). "When the glucose level of obese patients reached a certain level, glucose sensitivity is reduced, the insulin concentration in their body also increased, and even hyperinsulinemia and prediabetes symptoms appeared." (PMID 34721575, 2021). "It is well-known that insulin levels rapidly increase in severe burns in a process called post-burn hyperinsulinemia." (PMID 34068151, 2021).